KRAS (KRas proto-oncogene, GTPase)
Diseases named in the same sentence as KRAS in open-access papers (continued):
Sharing a sentence is not in itself a finding about the gene and the disease.
non-small cell lung carcinoma (continued). "Treatment with NBF-006 significantly inhibits tumor growth in KRAS mutant non-small cell lung cancer (NSCLC) xenograft models and prolongs survival in surgically implanted orthotopic lung tumor mice without toxicity." (PMID 35057033, 2022). "For the first-line treatment of KRAS mutant non-small cell lung cancer (NSCLC) patients, immunotherapy or platinum-based chemotherapy are the main treatment method." (PMID 36376839, 2022). "The KRAS inhibitor, AMG-5101 (brand name Lumakras, generic name sotorasib) recently obtained FDA approval for the treatment non-small cell lung cancer patients who have the KRAS G12C mutation." (PMID 36418474, 2022). "Current dose exploration and dose expansion clinical trial combining sotorasib with pembrolizumab (NCT04185883) is undergoing, which included participants with KRAS p.G12C advanced non-small cell lung cancer." (PMID 36059606, 2022). "FAK is required for promoting DNA damage repair in KRAS non-small cell lung cancer (NSCLC) cells and FAK inhibitors augment the cytotoxic effects of IR by increasing DNA damage." (PMID 35954292, 2022). "First, previous work in KRAS*-driven non-small cell lung cancer reported differential dependencies on glutaminolysis in vitro in cell lines versus in vivo in lung tumors." (PMID 35815941, 2022). "CREG1, the cellular repressor of E1A-stimulated genes, a downstream effector of KRAS which identifies in Glycoproteomic Approach as a positive regulator of CREG1 in Non-small Cell Lung Cancer Cells." (PMID 35057823, 2022). "Sotorasib is the first small molecule inhibitor against KRAS G12C mutations and was approved by the FDA for the treatment of non-small cell lung cancer (NSCLC) in 2021." (PMID 36139627, 2022). "In the Phase II trial NCT01951690, Defactinib monotherapy showed modest clinical activity in heavily pretreated KRAS mutant non-small cell lung carcinoma (NSCLC) patients." (PMID 35216114, 2022). "For example, a sub-clonal evolution of MET amplification in KRAS G12C non-small cell lung cancer cells that have become resistant to AMG510 in vitro." (PMID 36359850, 2022). "Another example of the methods being tested is the intranasal administration of a lentivirus vector expressing let-7a in a model of human non-small-cell lung cancer, resulting in inhibition of the growth of KRAS-dependent lung tumors." (PMID 35269947, 2022). "Non-small cell lung cancer (NSCLC) is heterogeneous and KRAS G12C is the most prevalent of the KRAS mutations." (PMID 35892709, 2022). "Kirsten rat sarcoma viral oncogene (KRAS) belongs to the RAS protein family, and KRAS mutation is a common type of mutation in non-small cell lung cancer." (PMID 35620280, 2022). "Ganetespib, a heat shock protein 90 inhibitor, used in clinical trials for the treatment of non-small cell lung carcinoma with EGFR, KRAS, or ALK mutations, was effective in all cell lines with a stronger inhibition in CRMM2." (PMID 35326726, 2022). "KRAS mutation was observed with very high frequencies in multiple KRAS-driven tumors, such as pancreatic, colorectal, and non-small cell lung carcinoma." (PMID 36144542, 2022). "For example, Qian and colleagues explored the role of macropinocytosis in A549, a human non-small cell lung cancer (NSCLC) cell line that is addicted to oncogenic KRAS." (PMID 35154489, 2022).
non-small cell lung carcinoma (continued). "For instance, KRAS- and LKB1-mutated epigenetic silencing of STING leads to facilitated immune escape in non-small cell lung cancer (NSCLC) cells." (PMID 35889509, 2022). "In non-small-cell lung cancer (NSCLC), concurrent mutations in the oncogene KRAS and tumor suppressor STK11 (also known as LKB1) confer an aggressive malignant phenotype, an unfavourability towards immunotherapy, and overall poor prognoses in patients." (PMID 35011738, 2022). "Non-small cell lung cancer samples with BRAF variants were less likely than expected to carry also alterations in EGFR and KRAS." (PMID 36275468, 2022). "In non-small cell lung cancer (NSCLC) the most common alterations are identified in the Kirsten rat sarcoma viral oncogene homolog (KRAS) gene, accounting for approximately 30% of cases in Caucasian patients." (PMID 36077640, 2022). "Pyrimidine synthesis has been recently discovered as a metabolic vulnerability and promising therapy target in KRAS/LKB1 mutant non-small-cell lung cancer and PTEN mutant cancer." (PMID 36122209, 2022). "Dong and colleagues reported that cilengitide reversed erlotinib resistance by inhibiting the Galectin-3/KRAS/RALB/TBK1/NF-κB signaling pathway in non-small cell lung cancer." (PMID 35142593, 2022). "The enrichment of KRAS signaling upon VHL restoration is probably related to the paradoxical function of HIF2α to constrain KRAS-AKT signaling in non-small cell lung cancer driven by KrasG12D." (PMID 35159281, 2022). "Kirsten Rat Sarcoma (KRAS) is one of the most frequently mutated human proto-oncogenes, and is highly prevalent in pancreatic, colorectal (CRC), prostate and non-small-cell lung carcinoma (NSCLC)." (PMID 33652552, 2021). "In non-small cell lung cancer (NSCLC), KRAS is mutated in around one third of patients, much more frequently than other oncogenic drivers e.g. EGFR (~15%), ALK rearrangements (~5%), MET mutations (~3%), for which targeted therapies are available." (PMID 33466360, 2021). "Overall, the most promising therapeutic results have been obtained with molecules targeting KRAS G12C, thus paving the way for a significant therapeutic improvement in non-small cell lung cancer." (PMID 34064352, 2021). "This study emphasized the role of HRAS and KRAS gene expression levels and their heterogeneity in non-small-cell lung cancer cases." (PMID 33549031, 2021). "We stratified non-small cell lung cancer cell (NSCLC) models by EGFR and KRAS mutations and then looked at the average gene essentiality for all genes within each of these 4 subtypes of NSCLC." (PMID 34663427, 2021). "The phase II clinical trials for Defactinib (VS-6063) have been completed in patients with KRAS mutant non-small cell lung cancer (NSCLC) and the drug was generally well tolerated and suitable for long-term dosing." (PMID 35201485, 2021). "Phase II clinical trials of VS-6063 in patients with KRAS mutant non-small cell lung cancer have been completed." (PMID 34299525, 2021). "Oncogenic mutations at codons Gly 12, 13, and Gln 61 of KRAS occur in ~86% of KRAS-mediated human cancers, including pancreatic (90%), colon (40%), and non-small cell lung cancer (20%)." (PMID 33917906, 2021). "Our study demonstrates data on the frequency of KRAS and EGFR mutations in a large cohort of patients diagnosed with non-small cell lung cancer that underwent surgical resection treatment over a defined period in Halifax, Canada." (PMID 33956842, 2021).
non-small cell lung carcinoma (continued). "In a chemical and genetic screen to identify biological targets that support tumorigenesis in non-small cell lung cancer (NSCLC), COPI coatomer subunits were identified as being required for the growth of NSCLC cells carrying mutations in KRas and LKB1." (PMID 34725334, 2021). "Studies reported that SHP2 is required for the growth of KRAS-mutant non-small-cell lung cancers (NSCLCs), and its inhibition leads to a potential antitumor therapy." (PMID 33777940, 2021). "GATA2 has a key role in hematopoietic development and the key to KRAS-driven non-small-cell lung cancer; its GC content (65.2%) is higher than the AT content (34.8%)." (PMID 34205890, 2021). "KRAS, an EGFR-induced cell signaling downstream mediator, has been found to be mutated in about 25% of Non-small cell lung cancer (NSCLC) cases, whereas in melanoma, KRAS mutations are rare and found in only 1.7% of the cases." (PMID 33807778, 2021). "The effects of specific KRAS inhibitors, such as AMG-510 and MRTX849 targeting specific G12C mutations (KRASG12C) are being investigated in ongoing clinical trials in non-small cell lung cancer." (PMID 34884633, 2021). "Factors contributing to the disease heterogeneity of KRAS-mutant non-small-cell lung cancer (sources)." (PMID 33809660, 2021). "Glutaminolysis has an important role in carcinogenesis and some KRAS-driven non-small cell lung cancers (NSCLC), among cancers with the worse outcome, display glutaminolysis dependency." (PMID 33923958, 2021). "Quick and reliable testing of EGFR and KRAS is needed in non-small cell lung cancer (NSCLC) to ensure optimal decision-making for targeted therapy." (PMID 34344387, 2021). "In several tumor types, such as KRAS-mutant pancreatic and non-small-cell lung cancer, autophagy has emerged as a targetable process of interest." (PMID 34199986, 2021). "Sotorasib (AMG 510), a KRAS (G12C) inhibitor developed by Amgen®, produced significant results in phase 1 clinical trial for non-small cell lung cancer, rapidly emerging as the next new drug for lung cancer." (PMID 33917906, 2021). "Kirsten Rat Sarcoma viral oncogene homolog (KRAS) is the most frequently altered oncogene in Non-Small Cell Lung Cancer (NSCLC)." (PMID 35083149, 2021). "Targeting effector signaling in KRAS-driven non-small cell lung cancer has resulted in limited efficacy in the clinic." (PMID 33514834, 2021). "The FDA recently granted accelerated approval for the first-in-class KRAS (G12C) inhibitor sotorasib (Amgen Inc.)for patients with locally advanced or metastatic non-small cell lung cancer." (PMID 35141142, 2021). "Even in non small cell lung cancer (NSCLC), frequency of KRAS mutations differs between Caucasians and East Asian populations (25–50% and 5–15% respectively)." (PMID 32552660, 2020). "AMG510 and MRTX1257 were the first ones to be developed as drugs to target KRAS G12C mutant for non-small cell lung cancer." (PMID 31941155, 2020). "Recently, higher levels of DNA pol β were associated with DDP resistance, and the in vitro inhibition of DNA pol β with pamoic acid restored DDP sensitivity in KRAS (G12C) over-expressing non-small cell lung cancer (NSCLC)." (PMID 32847049, 2020). "EZH2 high expression or its synergistic action with KRAS and BRAF mutations affects the prognosis of non-small-cell lung cancer." (PMID 33299862, 2020). "A recently published study shows a role of asparagine in attenuating ATF4-mediated apoptosis during nutrient stress in response to KRAS signaling in non-small-cell lung cancer (NSCLC)." (PMID 32266129, 2020). "Here we provided a novel signal axis in which KRAS was activated by its upstream genes and participated in the progression of non-small cell lung cancer (NSCLC)." (PMID 33005174, 2020).
non-small cell lung carcinoma (continued). "In this Phase 1 study, the pan-HER inhibitor dacomitinib was combined with the MEK1/2 inhibitor PD-0325901 in patients with KRAS-mutant colorectal, pancreatic and non-small-cell lung cancer (NSCLC)." (PMID 32147669, 2020). "Half of the KRAS-mutant NSCLC (non-small-cell lung cancers) express the homeobox protein HOXC10, which triggered tumour regression in xenografts and PDX (patient-derived xenografts) models in vivo." (PMID 33375038, 2020). "For example, EGFR/KRAS/ALK in non-small cell lung carcinoma, or BRAF, NRAS in melanoma, in agreement with the ESMO guidelines." (PMID 31787752, 2020). "Non-small cell lung cancer (NSCLC) constitutes about 85% of all lung malignancies, out of which 30% harbor KRAS mutations that are associated with aggressive, therapy-resistant tumors." (PMID 32034305, 2020). "Of note, KRAS-related studies that included general non-small cell lung cancer (NSCLC) population instead of LADC patients should be very carefully evaluated." (PMID 32548736, 2020). "Here, using two non-small cell lung carcinoma (NSCLC) cell lines, one harboring a fast-cycling KRAS mutation and one with wildtype RAS, we show that RASSF1A suppression downregulates DAB2IP." (PMID 33348649, 2020). "This study focuses on the management of patients with mCRC, but KRAS, NRAS or BRAF mutations testing is also relevant in other cancers like metastatic melanoma or non-small cell lung cancer." (PMID 30811471, 2019). "Further studies are necessary to clarify the role of KRAS mutations and MYC amplifications in MET-altered non-small-cell lung cancer." (PMID 30459450, 2019). "Recently, oncogenic KRAS has been identified as a key regulator of the transcriptional response to nutrient deprivation in non-small cell lung cancer and ATF4, as a key transcription factor regulated by KRAS to support amino acid homeostasis." (PMID 31071975, 2019). "For instance, malfunction of autophagy inhibits KRAS–triggered tumorigenesis of non small-cell lung cancer and DEN-induced HCC." (PMID 30849993, 2019). "This review will discuss the most recent findings on mutant KRAS metabolic reliance in tumor models of pancreatic and non-small-cell lung cancer, also highlighting the role that these metabolic adaptations play in resistance to target therapy." (PMID 31544066, 2019). "KRAS-driven non-small cell lung cancers also rely on the nuclear export receptor XPO1, which clears nuclear IκBα and supports NF-κB activity." (PMID 31681559, 2019). "In this review, we update the recent clinically relevant aspects of the pathobiology of KRAS-mutant non-small cell lung cancer (NSCLC), mainly focusing on tumor heterogeneity, therapeutic implications, and new treatment opportunities." (PMID 31612108, 2019). "The cell cycle regulator CDK4 also displays a synthetic lethal relationship with KRAS in non-small cell lung cancers." (PMID 31681559, 2019). "A phase II single arm study enrolled 37 patients with metastatic KRAS- or epidermal growth factor receptor (EGFR)-mutated, treatment-naïve, non-small cell lung cancer." (PMID 29799479, 2018). "This approach decreased the tumor load in a KRAS (K-ras; a proto-oncogene)-activated non-small cell lung cancer mouse model." (PMID 29515800, 2018). "Inhibition of AKT1 enhanced migration and invasion in KRAS- or EGFR-mutant non-small cell lung cancer (NSCLC) cells." (PMID 28765579, 2017). "EGFR (exon 19 and exon 21) mutations in patients with advanced non-small cell lung cancer (NSCLC) treated by EGFR-TKIs are associated with a better survival; while KRAS mutations predict a worse prognosis." (PMID 28430611, 2017).
non-small cell lung carcinoma (continued). "In non-small cell lung cancer it was shown that ALK rearrangements (that were previously thought to be mutually exclusive with activating EGFR and KRAS mutations) can be found together with EGFR mutations in rare cases." (PMID 28549417, 2017). "A differential contribution of RAF kinases was also reported in KRAS-driven non-small cell lung carcinoma." (PMID 28497782, 2017). "Selumetinib plus docetaxel in previously treated patients with KRAS-mutant advanced non-small cell lung cancer (NSCLC), and selumetinib plus dacarbazine in patients with BRAF-mutant metastatic melanoma, have more recently been assessed in phase II trials." (PMID 28264648, 2017). "Selumetinib, in combination with some existing cancer drugs (eg, docetaxel, erlotinib, cetuximab), is being/has been investigated in clinical trials for treating KRAS-MT solid tumors including non-small-cell lung cancer (NSCLC) and CRC." (PMID 27965461, 2017). "Here, we report our experience using next generation sequencing (NGS) to examine AKT1, BRAF, EGFR, ERBB2, KRAS, NRAS, and PIK3CA genes in 1006 non-small cell lung cancers in a clinical diagnostic setting." (PMID 29228562, 2017). "KRAS p.G12V was reported as a biomarker for poor prognosis in resected non-small cell lung cancer (NSCLC) as it exhibited a worse overall survival (OS) and higher recurrence rates." (PMID 28769798, 2017). "The principal mutations of EGFR, ALK, KRAS, BRAF, PIK3CA and HER2 were analyzed in 44 patients with non-small-cell lung cancer." (PMID 26968843, 2016). "Other investigators have already applied this in KRAS mutant mouse models of non-small-cell lung carcinoma and pancreatic adenocarcinoma and in mouse “co-clinical trials”." (PMID 26910118, 2016). "Inhibition of CDK4 was found to be synthetically lethal in vitro and in vivo in KRAS mutant non-small cell lung cancers." (PMID 27167191, 2016). "Murine knockout studies have shown an essential role for either RALA or RALB in KRAS driven non-small cell lung cancer cell proliferation." (PMID 27556501, 2016). "It has been proven that epidermal growth factor receptor (EGFR), anaplastic lymphoma kinase (ALK), and KRAS are common driver genes in non-small cell lung cancer (NSCLC)." (PMID 27760592, 2016). "In non-small cell lung cancer, KRAS has a profound influence on glutamine metabolism through regulation of ME1 and GOT1, the high expression of which has been shown to correlate with poorer prognosis after radiotherapy." (PMID 27924922, 2016). "Nowadays, with the recognition of EGFR and KRAS gene mutations, MET amplification and EML4-ALK rearrangements, new therapies directed against defined molecular targets profoundly impact on the non-small cell lung cancer (NSCLC)." (PMID 27050281, 2016). "Here we investigated the role of PAK1/Crk axis in transduction of the oncogenic KRAS signal in non-small cell lung cancer (NSCLC)." (PMID 25956913, 2015). "Here, we show that non-small cell lung cancer cell lines harboring differing isoforms of mutant KRAS, can be broadly divided into EGFR/HER dependent and EGFR/HER independent groups." (PMID 25992771, 2015). "A mouse model of non-small cell lung cancer tumors with LKB1 (gene expression product of STK11) and KRAS mutation showed specific response to phenformin." (PMID 26431491, 2015). "KRAS mutations occur in approximately 20% of all human cancers and are particularly prevalent in pancreatic ductal adenocarcinoma (PDAC, ~90%), non-small cell lung cancer (NSCLC, ~25%) and colorectal cancer (~40%)." (PMID 25946136, 2015).